G6PD (glucose-6-phosphate dehydrogenase)
Diseases named in the same sentence as G6PD in open-access papers (continued):
Sharing a sentence is not in itself a finding about the gene and the disease.
G6PD deficiency (continued). "G6PD deficiency is not a modifiable attribute, and in this study we found that the proportions of G6PD deficient individuals varied by study village, by ethnicity, and by gender." (PMID 37045879, 2023). "Many of the participants underestimated G6PD with 349 (76%) participants not believing that G6PD deficiency anemia can lead to death or handicap." (PMID 38125694, 2023). "Testing for G6PD deficiency status for in utero fetuses is difficult, invasive, and rarely done and PQ administration for pregnant women (regardless of their G6PD status) is often contraindicated." (PMID 37045879, 2023). "For the remaining 72 samples with impaired G6PD activities (5 with G6PD deficiency and 67 with intermediate deficiency), no mutation was detected by HRM assays." (PMID 37967096, 2023). "Progress has been slowed by low uptake of antihypnozoiticidal treatment with 8-aminoquinoline drugs due to fears of hemolysis in patients with G6PD deficiency, compounded by lack of access to G6PD testing." (PMID 35041650, 2022). "Some studies have found that G6PD deficiency without evidence of hemolysis is associated with a lower platelet count than G6PD-normal, but other studies have not found such an association." (PMID 36407223, 2022). "Association between pyruvate levels and G6PD polymorphisms was validated in an independent cohort and novel murine models of G6PD deficiency (African and Mediterranean variants)." (PMID 36395887, 2022). "A causal role of this correlation is established in humanized murine models of G6PD deficiency, since the same metabolic change is seen in RBCs that differ only in their form of G6PD (African or Mediterranean variants versus nondeficient human form)." (PMID 36395887, 2022). "Supporting our findings, another small study that compared 6 patients with G6PD deficiency with 11 patients with normal G6PD reported no major differences except for the lowest PaO2/FiO2 (p < 0.05) and lowest Hb levels in the G6PD deficient group." (PMID 36466438, 2022). "Independent of maternal, obstetric and neonatal risk factors, G6PD deficiency hemizygotes or homozygotes had an adjusted Hazard Ratio (AHR) of 4.78 (95%CI:3.35–6.84; P<0.001) for developing NH in the first week of life compared to G6PD wild type genotypes." (PMID 36962413, 2022). "The very low prevalence or absence of G6PD deficiency in Ethiopia prompted the approval of PQ administration without G6PD testing, with close monitoring of patients." (PMID 35392979, 2022). "This patient had no known underlying risk factors, including a normal BMI, normal renal function, two negative glucose-6-phosphate-dehydrogenase (G6PD) deficiency tests, and surprisingly a negative Coombs test." (PMID 36225525, 2022). "Glucose-6-phosphate dehydrogenase (G6PD) deficiency and Duffy-negative blood groups are two red blood cell (RBC) variations that can confer protection against malaria." (PMID 35527254, 2022). "Mild anemia was found in 10 persons with partial G6PD deficiency in females but not in G6PD deficient males." (PMID 36248708, 2022). "G6PD deficiency is common in sub‐Saharan Africa and the predominant alleles: 202A and 376G as G6PDA− are responsible only for approximately 12% of enzyme activity compared to the wild‐type 202G and 376A G6PD B allele." (PMID 33938598, 2021). "Although novel G6PD mutation was not identified in our study, G6PD Aures and G6PD Valladolid were firstly identified among our Thai children affected with G6PD deficiency." (PMID 33628497, 2021). "The preliminary database showed that, overall, 6.3% of Mauritanian men and 1.5% of Mauritanian women are affected by G6PD genetic polymorphisms leading to the African-type G6PD deficiency, and that the Mediterranean-type G6PD deficiency is absent." (PMID 34353361, 2021).
G6PD deficiency (continued). "Second, before primaquine is administered to non-anaemic women, a precise measurement of G6PD enzyme activity with a reliable quantitative assay is required, as qualitative screening tests cannot reliably detect G6PD deficiency in heterozygous women." (PMID 34353361, 2021). "Comprehensive analysis of the G6PD mutation and genotype-phenotype correlation of G6PD deficiency in Thai populations have never been studied." (PMID 33628497, 2021). "While able to accurately identify G6PD deficiency, the FST is less accurate in discriminating females with intermediate G6PD activity who may be heterozygous, with one normal and one deficient G6PD gene allele." (PMID 34543346, 2021). "CareStart G6PD RDT was positive in all of these five male patients, indicating G6PD deficiency." (PMID 34353361, 2021). "The diagnoses clustered within the phagocyte diseases consisted of autosomal recessive chronic granulomatous disease (AR-CGD) (n=2/5; 40%), G6PD deficiency (n=2/5;40%) and MKL1 deficiency (n=1/5; 20%), based on pathogenic variants in NCF1, G6PD and MKL1, respectively." (PMID 34992599, 2021). "The program has supplied few kits in places where based on research there are high prevalence of G6PD deficiency but in most of [the] areas there are no G6PD tests." (PMID 33757538, 2021). "Further analysis in a subset of patients without mild to moderate anaemia was not performed because only one patient with the G6PD genotype associated with African-type G6PD deficiency was non-anaemic." (PMID 34353361, 2021). "The prevalence of G6PD mutations in 725 people living in a malaria endemic area along the Thai–Myanmar border was determined to be 27.17 % by HRM, which is greater than the prevalence of G6PD deficiency determined by the WST-8 phenotypic assay (20.55 %)." (PMID 33879156, 2021). "Historically, the most critical MDL for managing G6PD deficiency has been severe G6PD deficiency, and more recently the new antimalarial drug Kozenis is not recommended for individuals with < 70% G6PD activity." (PMID 34543346, 2021). "G6PD deficiency POC test permits clinical diagnostic decisions either to administer anti-malarial drugs/SP or not in resource-limited settings and useful for improving health outcomes and the cost of accessing G6PD testing services." (PMID 32316233, 2020). "Evidence indicates that qualitative G6PD tests do not detect all clinically relevant cases of G6PD deficiency, particularly in female neonates." (PMID 32766454, 2020). "Although 16.5% (n = 188) of patients had a G6PD activity below laboratory reference values (N: 10–14 U/HgL), only 6.9% (n = 188) of patients had an intermediate G6PD deficiency, and no severe deficiency was reported (Supplement S1)." (PMID 32456698, 2020). "In Papua the treatment guidelines changed in March 2006 from the lower dose to the higher dose regimen, but since G6PD testing was not available, patients were treated without prior exclusion of G6PD deficiency." (PMID 33175835, 2020). "Safe access to the most effective treatment options for Plasmodium vivax malaria are limited by the absence of accurate point-of-care testing to detect glucose-6-phosphate dehydrogenase (G6PD) deficiency, the most common human genetic disorder." (PMID 32766454, 2020). "The frequency of G6PD deficiency in infants with jaundice is well reported, however, the frequency of G6PD variants with G6PD deficiency in the infants with jaundice has not be studied to a great extent." (PMID 32680472, 2020). "Individuals with glucose-6-phosphate dehydrogenase (G6PD) deficiency have higher risk for P. knowlesi infection but not with other Plasmodium species infections than individuals with no G6PD deficiency." (PMID 32120949, 2020). "G6PD testing prior to the initiation of patients on hydroxychloroquine is not indicated due to the low incidence of G6PD deficiency in that patient population and a very low risk of anemia in the patients treated with the drug." (PMID 32884875, 2020).
G6PD deficiency (continued). "The demonstrated test sensitivity of >95% in detecting G6PD deficiency in male volunteers, and high negative predictive value exceeding 95%, meet the thresholds for a G6PD diagnostic test as recommended by the WHO." (PMID 32004348, 2020). "Although rapid diagnostic tests to detect G6PD deficiency are available, they cannot detect deficiency in heterozygous female patients with intermediate G6PD activity, and they have not been distributed widely." (PMID 30500927, 2019). "The clinical decision to give primaquine as radical treatment for P. vivax malaria and mixed infections in this vulnerable group without G6PD testing should be made with great caution, particularly in areas with a higher prevalence of G6PD deficiency." (PMID 30940140, 2019). "Although all patients with favism are G6PD-deficient, many patients with G6PD deficiency can ingest FBs without clinical symptoms." (PMID 30823938, 2019). "The remaining G6PD mutations were identified in male neonates, and most of them did not suffer from G6PD deficiency." (PMID 31862010, 2019). "However, as G6PD deficiency is prevalent in malaria endemic areas in Lao PDR, and severe complications can result in the case of G6PD Viangchan mutation, G6PD screening has the potential to avoid unnecessary loss of lives in these endemic areas." (PMID 30866940, 2019). "Although G6PD deficiency in RBC has gained a lot of attention and a number of studies have enlightened many aspects of this enzyme defect, research on the deficient activity of G6PD in muscle cells is scarce." (PMID 31089417, 2019). "As G6PD deficiency was previously reported in a limited number of PAH cases, we tested whether iPAH patients exhibit underlying G6PD alterations in erythrocytes." (PMID 30161219, 2018). "Since detection of G6PD deficiency in PAH patients could be masked by increased hematopoiesis, other measurements such as G6PD protein concentration or reticulocyte markers are advisable." (PMID 30161219, 2018). "This provides radical cure in a single dose, but as it should not be given to patients with less than 70% of normal G6PD activity, it will require deployment of a new G6PD deficiency test." (PMID 29672516, 2018). "Although the mean level of hemoglobin in patients with G6PD deficiency was lower than patients with normal G6PD level in this study, this difference was not statistically significant." (PMID 28875002, 2017). "Since oxidative stress may trigger hemolysis of senescent G6PD-deficient RBCs with reduced levels of NAPDH, severe G6PD deficiency is linked to severe hemolytic anemia induced by food (e.g., fava bean) and drugs (e.g., primaquine)." (PMID 28531196, 2017). "G6PD deficiency has been studied in recent years in this border population (Banconeet al., 2014;Phompraditet al., 2011), but quantitative characterization of G6PD phenotypes in women has not been carried out yet at the population level." (PMID 29181452, 2017). "PQ in G6PD deficient compared to G6PD replete people Five controlled observational cohorts evaluated changes in haemoglobin when 0.75 mg/kg PQ was given to people with and without G6PD deficiency." (PMID 28830424, 2017). "Prior to the commencement of this study, there were no data on prevalence of G6PD deficiency in Chittagong Division or malaria patients anywhere in the country, and no G6PD genotypic data of any form." (PMID 28356147, 2017). "Patients with G6PD deficiency did not present adverse reactions to CQ/PQ treatment; therefore, G6PD genotypes were not considered as a confounder variable in this population study." (PMID 27767381, 2016). "Separating G6PD deficiency in mild and severe deficiencies, or restricting the analysis to male patients only (that are haploid for G6PD) did not change the results (p>0.14 and p>0.49, respectively)." (PMID 27018585, 2016).
G6PD deficiency (continued). "Fear of haemolysis in G6PD deficient patients and the absence of a practical, low-cost rapid diagnostic test to diagnose G6PD deficiency have so far obstructed the wider use of this class of drugs." (PMID 27013512, 2016). "After adjusting for these parameters, a univariate analysis between G6PD status and hematological parameters showed that the absolute monocyte count was significantly different between those with and without a G6PD deficiency (P < 0.05)." (PMID 27109515, 2016). "Here, we simulated G6PD deficiency by constraining the G6PD flux to be no greater than 26 % of that in normal RBCs to understand its metabolic consequences." (PMID 27502771, 2016). "The single low dose (0.25mg/kg) of primaquine is clinically well tolerated and can be used safely without prior G6PD testing in populations with high prevalence of G6PD deficiency." (PMID 27010542, 2016). "WBCs number and neutrophils percentages in G6PD deficient patients compared with patients without G6PD deficiency were decreased, but were not statistically significant (p=0.77 and p=0.86 respectively)." (PMID 27974910, 2016). "The G6PD RDT always correctly classified male patients with severe G6PD deficiency, whereas the FST failed to do on two occasions—a serious problem imposing risk of harm with primaquine therapy." (PMID 26894297, 2016). "Many national malaria control programs recommend primaquine therapy without G6PD screening but with monitoring due to a broad lack of G6PD deficiency screening capacity." (PMID 25746733, 2015). "Recent studies have indicated that the CareStart G6PD test is non-inferior in the diagnosis of G6PD deficiency to the FST." (PMID 26416229, 2015). "Although primaquine is used for malaria prevention, no study has previously investigated the prevalence of G6PD variants and G6PD deficiency in the Republic of Korea (ROK)." (PMID 24853873, 2014). "There is no clinical data about these four G6PD deficiency mutants, and there is only limited information about G6PD Yucatan (K429E)." (PMID 25407525, 2014). "Of 1,044 blood samples tested using the CareStart G6PD test, none were positive for G6PD deficiency." (PMID 24853873, 2014). "While children with severe G6PD deficiency were not seen, G6PD values as low as 10.3% activity were identified." (PMID 23782846, 2013). "Using a cut-off number of negative cell >20% in the cytochemical assay to define G6PD deficiency, the prevalence of G6PD deficiency was closest to the molecular analysis (12.9% G6PD-deficient) compared to the others methods." (PMID 23965028, 2013). "Its cut-off value for G6PD deficiency determination is only 10-20% of the normal G6PD activity, which excludes patients with moderate enzyme deficiency and increases the risk of false-normal diagnosis." (PMID 23782846, 2013). "It is not certain how prevalent G6PD deficiency is in Cambodia (estimates range from 15–20%, the most common variant being G6PD Viangchan (871G>A)) and field studies are currently underway to investigate this." (PMID 22662135, 2012). "Despite extensive study of G6PD deficiency in Pakistani neonates, there has been no national interest in molecular characterization of G6PD gene." (PMID 22906047, 2012). "To date, only one large scale systematic study of G6PD gene mutations associated with G6PD deficiency has been undertaken for the Saudi Arabian population, but this study did not describe pan-gene G6PD haplotyping nor sequencing of introns." (PMID 23006493, 2012). "The ideal specification for a G6PD deficiency test is difficult to achieve as there is no defined acceptable cut-off of G6PD activity." (PMID 23130957, 2012). "Approximately 400 million people living in tropical and sub-tropical areas exhibit a G6PD deficiency, with a high diversity of variants, including the common G6PD B (wild type), G6PD A (nondeficient type), and G6PD A- (African deficient type)." (PMID 23316245, 2012).
G6PD deficiency (continued). "Few limitations were the small sample size of infants with G6PD deficiency and absence of G6PD variants analysis in G6PD normal infants." (PMID 22906047, 2012). "Under prevailing conditions, however, G6PD testing is rarely available and G6PD deficiency goes largely undetected, so our finding is unlikely to increase access to antirelapse drugs in the near future because of the continuing risk of haemolysis." (PMID 20520804, 2010). "The risk estimate of P. falciparum clearance at day 1, for homozygous, hemizygous or heterozygous G6PD deficiency versus G6PD-normal was not significant." (PMID 21092137, 2010). "Along the Thai-Burmese border, limited testing facilities for G6PD deficiency exist and primaquine is still prescribed in some clinics without confirming that the patient is G6PD normal." (PMID 21184691, 2010). "G6PD deficiency is common in most P. vivax malaria areas; moreover, in these areas G6PD testing is impractical due to a lack of funds, equipments or expertise." (PMID 20618990, 2010). "In contrast the patients without measured G6PD deficiency harboured significantly fewer non-synonymous G6PD polymorphisms (2/34 (6%), P = 0.001) but a similar number of synonymous polymorphisms (10/34 (29%), P = 1.0)." (PMID 19589177, 2009). "In our study other potential risk factors for G6PD deficiency, such as socio-economic status and migration, did not yield meaningful statistical results since the number of G6PD-deficient study participants was too small." (PMID 16780577, 2006). "Indonesia's malaria treatment guidelines do not require G6PD deficiency (G6PDd) screening prior to administering low-daily-dose PQ regimen, but future implementation of high-daily-dose PQ regimen (1 mg/kg/day over 7 days) will require G6PD screening." (PMID 41953713, 2026). "However, dapsone may induce hemolytic anemia independently of G6PD status, but there is a greater risk of RBC destruction in the presence of G6PD deficiency." (PMID 40799291, 2025). "Therefore, we present a case of low oxygen saturation during risperidone therapy in a patient with glucose-6-phosphate dehydrogenase (G6PD) deficiency and a hemoglobin variant that did not warrant acute intervention." (PMID 41306179, 2025). "Thirdly, the reliance on G6PD enzyme activity measurements for diagnosing G6PD deficiency might have overlooked individuals with mild or no symptoms, thereby complicating accurate clinical classification based on the disease’s presence." (PMID 38834682, 2024). "However, further research is needed as population-based studies are scarce on G6PD deficiency, and routine G6PD screening is not commonly practiced in healthcare facilities." (PMID 38383399, 2024). "If these results are confirmed by larger studies, G6PD activity could be measured early to promptly initiate radical treatment in patients without G6PD deficiency, or repeat the measurement if there is a deficit in the initial phase." (PMID 38725027, 2024). "The absence of a-thalassaemia and glucose-6-phosphate dehydrogenase (G6PD) deficiency could increase the risks for stroke by modulating the level of hemolysis, oxidative stress and blood rheology." (PMID 41542264, 2024). "A latent or, therefore, asymptomatic deficiency of G6PD may clinically manifest under the appropriate conditions, even when evidence of past or current clinical evidence of G6PD deficiency is lacking." (PMID 39100014, 2024). "In this study, a descriptive cross-sectional survey was conducted to determine the prevalence of G6PD deficiency in a population residing in Nay Pyi Taw, Myanmar, using a standard spectrophotometric assay, a rapid diagnostic test (RDT), Biosensor, and by genotyping G6PD variants." (PMID 37127600, 2023). "Despite genotyping females with G6PD deficiency, the overlap between the upper range of borderline and the lower range of normal G6PD activity could not be resolved." (PMID 37508669, 2023).